CSRP2 (cysteine and glycine rich protein 2)
Diseases named in the same sentence as CSRP2 in open-access papers (continued):
Sharing a sentence is not in itself a finding about the gene and the disease.
triple-negative breast carcinoma (1 paper, 2018). An invasive breast carcinoma which is negative for expression of estrogen receptor (ER), progesterone receptor (PR), and human epidermal growth factor receptor 2 (HER2). "Next, we analysed and compared CSRP2 and HIF-1α protein expression in 48 triple negative breast cancer tissue array samples, and the results were scored by a pathologist." (PMID 29976963, 2018).
cancer (13 papers, 2008 to 2025). A tumor composed of atypical neoplastic, often pleomorphic cells that invade other tissues. "Cysteine-rich protein 2 (CSRP2) has been recently implicated in the progression and metastasis of a variety of cancers." (PMID 33042270, 2020). "Therefore, the exact mechanisms underlying the role of CSRP2 in various cancers need to be scrutinized." (PMID 40764945, 2025). "Cysteine-rich protein 2 (CSRP2) has been implicated in many types of cancer." (PMID 34585646, 2021). "Here, we report that a LIM domain protein, cysteine-and glycine-rich protein 2 (CSRP2 [CRP2]) plays a vital role in the functional expression profile in myofibroblasts and cancer-associated fibroblasts (CAFs)." (PMID 37164693, 2023). "We have recently demonstrated that a LIM domain protein, cysteine and glycine-rich protein 2 (CSRP2 [CRP2]), plays a vital role in the functional expression of myofibroblasts and cancer-associated fibroblasts." (PMID 37899269, 2023). "Others that have been indirectly linked to cancer include HIST1H2AD, two zinc finger proteins (ZCCHC3, ZNF552), and CSRP2, CREBL2, and SERTAD3." (PMID 29282095, 2017). "Intriguingly, CSRP2 appears to have different functions in these three cancers." (PMID 33042270, 2020). "The demonstration that the Csrp2 gene is silenced during cellular transformation and CRP2 protein induces growth-inhibitory effects when overexpressed in cancer cells points to a critical role in the control of normal cell growth." (PMID 18713466, 2008).
tumor (12 papers, 2008 to 2026). "In addition, among basal-like tumour patients, those with high CSRP2 expression exhibit an increased risk for developing metastasis." (PMID 29976963, 2018). "Subsequently, it was demonstrated that the transcriptional suppression of Csrp2 is generally linked to the transformed state of cells suggesting that CRP2 might have tumor-suppressor activity." (PMID 18713466, 2008). "To assess the effect of CSRP2 knockdown on tumor formation in vivo, we transplanted U87-MG cells with CSRP2 knockdown and control cells into the brains of nude mice." (PMID 40764945, 2025). "Csrp2 not only exhibits significantly higher expression levels in tumor tissues compared to normal tissues but also demonstrates superior diagnostic performance compared to AFP, a traditional biomarker for HCC." (PMID 41323394, 2025). "To assess the effect of CSRP2 overexpression on GBM tumor formation in vivo, we transplanted U87-MG cells with stable CSRP2 overexpression and control cells into the brains of nude mice." (PMID 40764945, 2025). "Strong CSRP2 signals were very frequently associated with HIF-1α positive regions in both MCF-7 and MDA-MB-231 tumour xenografts." (PMID 29976963, 2018). "Looking for hints of a hypoxic expression profile, we found that CSRP2 was frequently upregulated in or near the centre of tumour nests, a presumably highly hypoxic region." (PMID 29976963, 2018). "In addition, CSRP2 overexpression promoted the malignancy of GBM cells and their tumorigenicity in an intracranial xenograft tumor model, whereas CSRP2 knockdown had the opposite effects." (PMID 40764945, 2025). "Furthermore, the effect of CSRP2 on tumor growth in vivo was analyzed following subcutaneous injection of HCT116/CSRP2 cells and control cells in nude mice." (PMID 33042270, 2020). "In addition, CSRP2 knockdown inhibited tumour cell invasion under hypoxia with an almost similar magnitude as HIF-1α knockdown." (PMID 29976963, 2018). "In addition, tumour sections were co-labelled for CSRP2 and HIF-1α." (PMID 29976963, 2018). "Western blot analysis substantiated these findings at the protein level, revealing significantly elevated expression of CCNA2, CSRP2, ILF2, KIF2C, RACGAP1, and VARS in HCC tissues versus adjacent non-tumor tissues." (PMID 41323394, 2025). "CSRP2 overexpression in GBM cells promoted proliferation, colony formation, migration, invasion, temozolomide resistance, and PMT in vitro and tumor formation in vivo." (PMID 40764945, 2025). "Western blotting revealed significantly elevated levels of CCNA2, CSRP2, ILF2, KIF2C, RACGAP1, and VARS proteins in HCC tissues compared to adjacent non-tumor tissues." (PMID 41323394, 2025). "CSRP2 was strongly upregulated in hypoxic, pimonidazole-stained, regions of both MCF-7- and MDA-MB-231-cell derived tumours." (PMID 29976963, 2018). "In addition, CSRP2 and HIF-1α exhibited partially overlapping distribution in successive tumour sections." (PMID 29976963, 2018). "By analyzing the tumor size in patients with clinical stage I+ II and stage III + IV, we found that CSRP2 expression in stage I + II, but not in stage III + IV, was related to tumor size." (PMID 33042270, 2020).
bone disorder (1 paper, 2024). "Notably, genes such as CSRP2, DDX1, RHBDL1, SEZ6L, and CTSK are involved in growth, development, locomotion, and bone disorders." (PMID 38788487, 2024).
CSRP2 also shares sentences with these, for which no sentence is quoted: acute lymphoblastic leukemia (2 papers); acute myelogenous leukemia (1); blood cancers (1); breast tumour (1); chronic myeloid leukemia (1); colon cancers (1); colorectal adenocarcinoma (1); desmoid tumor (1); encephalitis (1); heart failure (1); invasive breast carcinoma (1); lymphocytic leukemia (1); mantle cell lymphoma (1); viral myocarditis (1).